RNU6-993P (RNA, U6 small nuclear 993, pseudogene)
Gene: Small nuclear RNA gene on chromosome 19 (2,503,047 to 2,503,141, reverse strand). Ensembl gene ENSG00000252962.
Homologues: Orthologues: chimpanzee U6 (99% identical), macaque U6 (96% identical), mouse Gm25384 (79% identical), dog U6 (78% identical), rat U6 (78% identical), guinea pig U6 (75% identical). Paralogues in human: RNU6-15P (86% identical), RNU6-1060P (85% identical), RNU6-116P (85% identical), RNU6-19P (85% identical), RNU6-33P (85% identical), RNU6-378P (85% identical), RNU6-657P (85% identical), RNU6-1 (84% identical), RNU6-1071P (84% identical), RNU6-1171P (84% identical), RNU6-1266P (84% identical), RNU6-140P (84% identical), and 1286 more.